CCDC86 (coiled-coil domain containing 86)
Description:
Required for proper chromosome segregation during mitosis and error-free mitotic progression.
Synonyms: CYCLON; MGC2574; Cgr1
Tractability: Small molecule: a structure with a bound ligand is known. PROTAC: ubiquitination databases record sites on it; its protein half-life has been measured.
Gene: Protein-coding gene on chromosome 11 (60,842,113 to 60,851,081, forward strand). Ensembl gene ENSG00000110104.
Subcellular location: Nucleus; Chromosome; Nucleus, nucleolus
Subcellular location (Human Protein Atlas): Mitotic chromosome; Nucleoli; Nucleoli rim; Nucleoplasm
Gene Ontology:
Molecular function: protein binding; RNA binding
Biological process: chromosome segregation; mitotic nuclear division
Cellular component: chromosome; nucleolus; nucleoplasm; nucleus
Genetic constraint (gnomAD): Loss-of-function variants: 30 observed, 40.38 expected, observed/expected ratio (o/e) 0.74, 90% interval 0.56 to 1.01. The upper end of that interval is the gene's LOEUF score, 1.01, which puts it in group 4 of 6, group 1 being the genes least tolerant of losing a copy. Missense variants: 453 observed, 497.95 expected, observed/expected ratio (o/e) 0.91, 90% interval 0.84 to 0.98. Synonymous variants: 199 observed, 214.79 expected, observed/expected ratio (o/e) 0.93, 90% interval 0.82 to 1.04.
Homologues: Orthologues: chimpanzee CCDC86 (99% identical), macaque CCDC86 (95% identical), pig CCDC86 (76% identical), mouse Ccdc86 (70% identical), rat Ccdc86 (62% identical), guinea pig CCDC86 (56% identical), dog CCDC86 (27% identical), zebrafish ccdc86 (26% identical), tropical clawed frog ccdc86 (20% identical), Drosophila melanogaster CG14210 (16% identical), Caenorhabditis elegans Y40B1B.7 (14% identical).
Diseases named in the same sentence as CCDC86 in open-access papers:
CCDC86 is named in the same sentence as 12 diseases in open-access papers, as found by Europe PMC text mining. Sharing a sentence is not in itself a finding about the gene and the disease. The quoted sentences say what the papers report.
lymphoma (4 papers, 2013 to 2023). A malignant (clonal) proliferation of B- lymphocytes or T- lymphocytes which involves the lymph nodes, bone marrow and/or extranodal sites. "Furthermore, CCDC86 was identified to be an autonomous tumour growth driver that cooperates with MYC to drive aggressive lymphoma growth in vivo." (PMID 36695333, 2023).
breast carcinoma (1 paper, 2012). "Six of the 11 non-mitosis related genes were previously associated with poor survival in breast cancer patients: KRT17, MMP12, SLC7A5, SQLE, GABRP and PA2G4, but the remaining 5 had not been previously associated with cancer risk: CCDC86, NUP107, NUTF2, WASF1 and ELOVL6." (PMID 23077491, 2012).
glioma (1 paper, 2025). A benign or malignant brain and spinal cord tumor that arises from glial cells (astrocytes, oligodendrocytes, ependymal cells). "Taken together, these data provide evidence for the up-regulation of CCDC86 in glioma and its association with patient survival, suggesting its potential as a prognostic marker in glioma." (PMID 40837407, 2025). "The results indicated that high expression of CCDC86 in gliomas was associated with poor overall survival (Logrank_P = 1.77E-19; hazard ratio = 2.19 (1.84–2.6)." (PMID 40837407, 2025). "More importantly, Kaplan–Meier survival analysis unveiled a substantial association of CCDC86 expression with overall survival and disease-free survival in glioma patients, highlighting its potential as a prognostic marker for this disease." (PMID 40837407, 2025). "In this study, we explored the role of CCDC86 in glioma and its underlying mechanisms." (PMID 40837407, 2025). "Moreover, elevated CCDC86 level was associated with a worsened prognosis among glioma patients." (PMID 40837407, 2025). "Our results unveiled elevated expression levels of CCDC86 in glioma, correlating with unfavorable prognosis." (PMID 40837407, 2025). "Here, we investigated the expression of CCDC86 in human glioma tissues and cell lines by analyzing our cohort and publicly available molecular databases." (PMID 40837407, 2025). "Overall, our study provides compelling evidence supporting the pivotal role of CCDC86 in malignant processes within glioma cells." (PMID 40837407, 2025). "The impact of CCDC86 in glioma was further defined with the identification of ATF3 as a downstream target gene, a transcription factor pivotal in regulating genes involved in cellular stress and cell cycle progression." (PMID 40837407, 2025). "To further explore CCDC86's functional impact in glioma, we utilized three shRNAs (shCCDC86-1, shCCDC86-2, and shCCDC86-3) to target CCDC86, thereby suppressing its expression in U251 cells, which exhibited the highest endogenous CCDC86 levels." (PMID 40837407, 2025). "Functional assays demonstrated that CCDC86 knockdown attenuated glioma cell proliferation and migration while inducing apoptosis and cell cycle arrest in vitro and inhibited tumorigenesis in vivo." (PMID 40837407, 2025). "We uncovered a potential oncogenic role for CCDC86 in glioma progression and identified activating transcription factor 3 (ATF3) as a downstream target gene." (PMID 40837407, 2025). "One promising avenue for therapeutic intervention is CCDC86, a previously unexplored potential target in glioma." (PMID 40837407, 2025). "In conclusion, our study highlights the pivotal role of CCDC86 in glioma progression, suggesting its potential as a therapeutic target for the development of novel glioma treatments." (PMID 40837407, 2025). "Our study revealed a significant up-regulation of CCDC86 expression in glioma tissues, correlating notably with patient age, tumor recurrence, and pathological grade." (PMID 40837407, 2025). "Despite its significance in other cancers, the role of coiled-coil domain containing 86(CCDC86) in glioma remains largely unexplored." (PMID 40837407, 2025). "To bolster our findings, we analyzed CCDC86 expression in two normal human brain tissue samples and six human glioma samples sourced from the GEO database (accession number GEO: GSE134470)." (PMID 40837407, 2025). "Moreover, CCDC86 overexpression promoted glioma cell proliferation while inhibiting apoptosis, partially reversed by ERK inhibitor treatment." (PMID 40837407, 2025). "Functional assays were then performed to elucidate CCDC86's roles in glioma." (PMID 40837407, 2025). "We provide evidence demonstrating that CCDC86 modulates the activity of the mitogen-activated protein kinase (MAPK)/extracellular signal-regulated kinase (ERK) pathway, a crucial signaling cascade implicated in glioma progression." (PMID 40837407, 2025). "Our study aimed to elucidate the role of CCDC86 in glioma pathogenesis." (PMID 40837407, 2025).
glioma (continued). "In conclusion, our findings underscore the critical role of CCDC86 in promoting glioma progression." (PMID 40837407, 2025). "Despite its significance in other cancers, the role of CCDC86 in glioma remains unexplored." (PMID 40837407, 2025). "Consequently, suppressing ATF3 impeded glioma cell proliferation and migration, counteracting the oncogenic effects induced by CCDC86 overexpression." (PMID 40837407, 2025). "The findings unveiled a notable up-regulation of CCDC86 in glioma tissues." (PMID 40837407, 2025). "Moreover, our findings revealed that CCDC86 overexpression promoted glioma cell proliferation while inhibiting apoptosis, effects that were partially reversed by treatment with an ERK inhibitor." (PMID 40837407, 2025). "Targeting CCDC86 may emerge as a promising strategy for the development of novel glioma therapies." (PMID 40837407, 2025). "Furthermore, ATF3 emerged as a downstream target gene of CCDC86, as its knockdown could counteract the oncogenic effects induced by CCDC86 overexpression in glioma cells." (PMID 40837407, 2025). "In our investigation, we found that elevated CCDC86 expression promoted glycolysis by up-regulating ATF3 and activating the ERK/MAPK pathway, thus driving glioma tumorigenesis." (PMID 40837407, 2025). "In this section, this study aimed to assess the roles of CCDC86 and ATF3 in glioma development in vitro and in vivo." (PMID 40837407, 2025). "The analysis confirmed that CCDC86 was significantly overexpressed in gliomas compared with normal tissues (log2foldchange = 0.615; p < 0.001)." (PMID 40837407, 2025). "The interaction between CCDC86 and BHLHE40 appears to be crucial for the transcriptional activation of ATF3, which may contribute to the oncogenic properties of glioma cells." (PMID 40837407, 2025).
neuroblastoma (1 paper, 2023). Neuroblastoma (NB) is the most common solid, extracranial childhood tumor. "We have also shown that the expression of the CCDC86 gene is regulated by MYCN and has prognostic value in neuroblastoma." (PMID 36695333, 2023). "We also discovered that CCDC86 is a MYCN-regulated gene, the expression levels of which are of prognostic value in Neuroblastoma patients." (PMID 36695333, 2023). "Moreover, we identified CCDC86 as a MYCN-regulated gene, the expression levels of which represent a powerful marker for prognostic outcomes in neuroblastoma." (PMID 36695333, 2023).
cancer (5 papers, 2012 to 2025). A tumor composed of atypical neoplastic, often pleomorphic cells that invade other tissues. "CCDC86 was also shown to play a role in T-cell activation-induced cell death and studies have also linked CCDC86 expression with cancer progression." (PMID 36695333, 2023). "Although very little is known about CCDC86 biology, this protein has already emerged as an important predictor of cancer resistance and outcome in several studies." (PMID 36695333, 2023). "As the Kaplan–Meier curves show, high levels of CCDC86 strongly correlate with a very low survival rate in this type of cancer." (PMID 36695333, 2023). "Furthermore, ATF3 and ERK pathway-associated and glycolysis-related proteins were up-regulated in CCDC86 highly expressed cancer tissues compared with adjacent normal tissues with low CCDC86 expression." (PMID 40837407, 2025). "By stabilizing ATF3 expression, CCDC86 potentially enhances the pro-tumorigenic signaling mediated by ATF3, offering a new perspective on the role of coiled-coil domain-containing proteins in cancer biology." (PMID 40837407, 2025).
tumor (4 papers, 2013 to 2025). "This up-regulation was further scrutinized through Mann–Whitney U and Spearman rank correlation analyses, revealing a positive correlation of CCDC86 expression with patients' age, tumor recurrence, and pathological grade." (PMID 40837407, 2025). "Tumor growth was monitored, revealing that CCDC86 played a crucial role in promoting tumor cell growth, evidenced by an increase in both tumor volume and weight upon its overexpression." (PMID 40837407, 2025). "Recent research has shed light on the critical involvement of CCDC86 in oncogenesis and tumor progression." (PMID 40837407, 2025). "To investigate the roles of CCDC86/ATF3 in tumor growth, we conducted in vivo animal experiments." (PMID 40837407, 2025). "The results obtained from both cohorts are very similar and clearly show that high expression of CCDC86 is found in patients with MYCN amplifications and the expression level of CCDC86 positively correlates with tumour stage progression and malignancy." (PMID 36695333, 2023). "Additionally, our investigation unveiled a potential mechanism whereby CCDC86 activated the ERK signaling pathway through ATF3, thus influencing glycolysis to drive tumor progression." (PMID 40837407, 2025). "In fact, in stage 4 tumours (which are not metastatic), CCDC86 presents low expression." (PMID 36695333, 2023).
CCDC86 also shares sentences with these, for which no sentence is quoted: B-cell lymphoma (2 papers); diffuse large B-cell lymphoma (1); lung carcinoma (1); malignant melanoma (1); multiple myeloma (1); primary effusion lymphoma (1).